KEL (Kell metallo-endopeptidase (Kell blood group))
Description:
Zinc endopeptidase with endothelin-3-converting enzyme activity. Cleaves EDN1, EDN2 and EDN3, with a marked preference for EDN3.
Synonyms: CD238; ECE3; Kell
Tractability: Antibody: its Gene Ontology location is reachable by antibodies, with high confidence; UniProt places it where antibodies can reach, with medium confidence; UniProt predicts a signal peptide or a membrane-spanning region.
Gene: Protein-coding gene on chromosome 7 (142,941,114 to 142,962,363, reverse strand). Ensembl gene ENSG00000197993.
Subcellular location: Cell membrane
Subcellular location (Human Protein Atlas): Golgi apparatus; Plasma membrane; Cytosol; Nucleoplasm
Pathways (Reactome):
Signal Transduction: Peptide ligand-binding receptors
Gene Ontology:
Molecular function: metalloendopeptidase activity; protein binding; metallopeptidase activity
Biological process: protein processing; vasoconstriction; proteolysis
Cellular component: plasma membrane; membrane
Genetic constraint (gnomAD): Loss-of-function variants: 96 observed, 102.46 expected, observed/expected ratio (o/e) 0.94, 90% interval 0.79 to 1.11. The upper end of that interval is the gene's LOEUF score, 1.11, which puts it in group 4 of 6, group 1 being the genes least tolerant of losing a copy. Missense variants: 923 observed, 966.21 expected, observed/expected ratio (o/e) 0.96, 90% interval 0.9 to 1.01. Synonymous variants: 355 observed, 370.9 expected, observed/expected ratio (o/e) 0.96, 90% interval 0.88 to 1.04.
Homologues: Orthologues: chimpanzee KEL (99% identical), macaque KEL (93% identical), rabbit KEL (80% identical), dog KEL (74% identical), pig KEL (73% identical), mouse Kel (72% identical), guinea pig KEL (69% identical), rat Kel (69% identical), Drosophila melanogaster Nep1 (26% identical), Drosophila melanogaster Nep3 (26% identical), Caenorhabditis elegans nep-11 (26% identical), Caenorhabditis elegans nep-1 (24% identical), and 31 more. Paralogues in human: ECE2 (30% identical), ECE1 (30% identical), ECEL1 (27% identical), MMEL1 (26% identical), PHEX (23% identical), MME (23% identical).
Diseases named in the same sentence as KEL in open-access papers:
KEL is named in the same sentence as 14 diseases in open-access papers, as found by Europe PMC text mining. Sharing a sentence is not in itself a finding about the gene and the disease. The quoted sentences say what the papers report.
lupus (2 papers, 2020 to 2023). "To test the clinical significance of anti-KEL antibodies in pristane-induced lupus mice, we examined the ability of anti-KEL antibodies to clear K1 RBCs from circulation." (PMID 33101313, 2020). "Anti-KEL IgG in pristane-induced lupus mice included all IgG subclasses made in C57BL/6 mice." (PMID 33101313, 2020).
anemia (1 paper, 2025). A reduction in the number of red blood cells, the amount of hemoglobin, and/or the volume of packed red blood cells. "Pathology became evident during the third pregnancy and was manifested by litters with markedly fewer than 50% KEL+ pups at birth and anemia in KEL+ pups that did survive." (PMID 39264989, 2025).
autoimmune hemolytic anemia (1 paper, 2021). Autoimmune hemolytic anemia (AIHA) is an autoimmune disorder in which various types of auto-antibodies are directed against red blood cells causing their survival to be shortened and resulting in hemolytic anemia. "with polyclonal anti-Kell using the KELMed system and similar to what has been observed in humans for the KEL antigen in patients with autoimmune hemolytic anemia." (PMID 33777014, 2021).
breast carcinoma (1 paper, 2023). "A search for reports (PubMed) of known activities of these genes in breast cancer showed that only three (CHPF2, KEL, and CCT6P1) have not yet been associated with this cancer." (PMID 36900209, 2023).
COVID-19 (1 paper, 2022). A disease caused by infection with severe acute respiratory syndrome coronavirus 2. "Additionally, KEL, which is part of the complex Kell blood group system that contains many highly immunogenic antigens, was associated with a decreased risk of hospitalization as a result of COVID-19." (PMID 35239653, 2022). "Higher levels of LCTL, SFTPD, KEL, and ATP2A3 were solely associated with a decreased risk of hospitalization (ORs = 0.86–0.93), whilst higher levels of ICAM-1 were solely associated with a decreased risk of respiratory support/death of COVID-19 (OR = 0.84)." (PMID 35239653, 2022). "However, our Mendelian randomization analyses showed that higher BMI is causal for higher levels of the COVID-19 protective proteins SELE, KEL, SELL, and causal for lower levels of the COVID-19 risk increasing proteins C1GALT and RAB14." (PMID 35239653, 2022).
leukemia (1 paper, 2022). A malignant (clonal) hematologic disorder, involving hematopoietic stem cells and characterized by the presence of primitive or atypical myeloid or lymphoid cells in the bone marrow and the blood. "Being identified to be involved in regulating proliferation and differentiation of AEL cells, high expression of KEL has been proved to accelerate leukemia progression in vivo as well and always indicate poor prognosis." (PMID 35140839, 2022).
myeloid neoplasm (1 paper, 2022). Proliferation of myeloid cells originating from a primitive stem cell. "In addition, M6 cell lines, HEL and K562, showed higher expression of KEL than myeloid neoplasm cell lines." (PMID 35140839, 2022).
tumor (7 papers, 2015 to 2023). "In general, these results demonstrated that KEL enhanced proliferation of tumor cells and was strongly associated with the progression and prognosis of AEL." (PMID 35140839, 2022). "Maintaining cell viability and differentiation, KEL also played parts in the immune evasion of tumor cells." (PMID 35140839, 2022). "Since KEL is a membrane protein on the surface of tumor cells, whether its ligands exist in immune cells and what the ligands are?" (PMID 35140839, 2022). "However, how KEL modulates PD-L1 expression and their interactions in tumor immune escape still need to be investigated." (PMID 35140839, 2022). "And the results proved that KEL could promote tumor cell proliferation." (PMID 35140839, 2022). "Six sEV proteins were identified, namely, GCLM, KEL, APOF, CFB, PDE5A, and ATIC, which properly distinguished normal control, early neoplasia, and advanced neoplasia patients from each other." (PMID 34589434, 2021). "The present study identified six sEV proteins, namely, GCLM, KEL, APOF, CFB, PDE5A, and ATIC, that could distinguish early neoplasia, advanced neoplasia, and normal controls from each other well." (PMID 34589434, 2021). "Also, the availability of patient DNA from the non tumoral tissue highlighted that the SNVs identified in the tumor tissue and Chor-IN-1 cell line were mainly germline, with four exceptions involving TECTA, SART3, KEL and MUC1 genes." (PMID 28835717, 2017). "Among the genes that are mutated between 5 to 20% in TCGA GBM tumor samples, we found mutations in NF1, SPTA1, TCHH and ATRX genes, although, the other genes like PIK3R1, PIK3CA, RB1, IDH1 and KEL were not mutated in any cell line." (PMID 26496030, 2015).
cancer (4 papers, 2021 to 2025). A tumor composed of atypical neoplastic, often pleomorphic cells that invade other tissues. "The downregulation of their expression is associated with better prognosis in several cancers, such as XK in ACC, CNNM4 in READ, KEL in CESC, CNNM3 in KIRC, as well as CNNM2 in LGG and KIRC." (PMID 41174507, 2025). "The mutation rates of different MHGs varied widely across cancer tissues, with ANK3 having the highest mutation rate (47%), followed by KEL (18%), TRPM7 (16%), KCNA1 (13%), CNNM2 (9%), CNNM1 (9%), TFAP2B (9%), CNNM4 (9%), XK (7%), and EDN3 (5%)." (PMID 41174507, 2025). "Briefly, the high expression of seven blood group antigen genes, i.e., FUT7, AQP1, P1, C4A, AQP3, KEL, and DARC, was significantly associated with good prognosis in six types of cancers, i.e., KIRC, HNSC, LUAD, CESC, SARC, MESO." (PMID 35955933, 2022). "On the contrary, high expression of four genes, i.e., KEL, GCNT2, P1 and ERMAP, was associated with a higher cancer grade in LGG and HNSC." (PMID 35955933, 2022).
KEL also shares sentences with these, for which no sentence is quoted: adenocarcinoma (1 paper); adenoma (1); erythroleukemia (1); glioma (1); rectal cancer (1).